CD4 (CD4 molecule)
Diseases named in the same sentence as CD4 in open-access papers (continued):
Sharing a sentence is not in itself a finding about the gene and the disease.
Sepsis (continued). "To further study the impact of Mdivi-1 on the apoptosis of CD4+ T cells in sepsis, we used LPS (100 ng/mL, 24 h) stimulation in vitro." (PMID 31263382, 2019). "The functional status of CD4+ T cells is essential for the immune response in the setting of sepsis." (PMID 30881224, 2019). "The proliferative arrest of CD4+ T cells that were compromised by sepsis was also improved by the central administration of 10 μg BoxA, but no significant alteration was observed at a dose of 1 μg BoxA." (PMID 30881224, 2019). "MLN DCs proved superior to systemic SP DCs in increasing CD4 T-cell proliferation in our experimental sepsis model." (PMID 31323786, 2019). "In this study, we have demonstrated, for the first time, that the HMGB1/PTEN/β-catenin signaling represents a novel regulatory pathway to induce CD4+CD25+Foxp3+ Tregs in sepsis-induced lung injury." (PMID 31402909, 2019). "Tunicamycin induced ER stress and eliminated the protective effect of Mdivi-1 treatment on CD4+ T cells during sepsis." (PMID 31263382, 2019). "Central treatment with BoxA improved the abnormal response of CD4+ T cells in sepsis by enhancing the expression of IFN-γ and decreasing that of IL-4, following an increase in the ratio IFN-γ/IL-4." (PMID 30881224, 2019). "In our study, our data demonstrated that Mdivi-1 increased the survival rate of CLP mice and reduced apoptosis of CD4+ T cells in experimental sepsis." (PMID 31263382, 2019). "The proliferation of CD4+ T cells was inhibited in the sepsis group when compared to the sham group." (PMID 30881224, 2019). "In our study of human sepsis, expression of the signature Th17 transcription factor and of surface IL-23R were reduced in CD4+ lymphocytes of septic patients." (PMID 31658288, 2019). "Previous studies have demonstrated that patients with sepsis show skewed CD4+ T cells responses, polarised towards Th2 and Treg responses with depletion and impairment of Th1 cells." (PMID 31658288, 2019). "Apoptosis of CD4+ T cells is the main pathophysiological mechanism of immune function inhibition in the pathogenesis of sepsis." (PMID 31507440, 2019). "Literature have shown an improved survival rate in experimental sepsis after adoptive transfer of small numbers of ex vivo activated CD4+ CD25+ Treg from healthy to septic animals." (PMID 31191818, 2019). "During sepsis both CD4+ and CD8+ T cell populations drop considerably, and, like myeloid cells, the magnitude of the drop is correlated closely with patient survival." (PMID 31281814, 2019). "Here, we investigated the role of the mTOR pathway in CD4+ T-cell survival in a mouse model of rapidly progressive lethal sepsis induced by severe invasive candidiasis and explored the possible mechanism." (PMID 31668132, 2019). "In the patients in the acute phase of sepsis, the expression of PD-1 on both CD4+ T cells and CD8+ T cells was significantly elevated compared with that in the controls (P < 0.05)." (PMID 31440257, 2019). "The administration of BoxA reversed the proliferative arrest of CD4+ T cells during the course of sepsis and was accompanied by the elevated expression of IL-2 (both protein and mRNA) when compared with the sepsis group." (PMID 30881224, 2019). "CD4+ T cells from patients with infection predominantly expressed effector-memory or terminally differentiated phenotypes but CD4+ T cells from patients with severe sepsis predominantly expressed naive phenotypes (p<0.0001)." (PMID 31658288, 2019). "Our study demonstrates long-lasting impairments in CD4+ T-cell responses despite rapid recovery of T-lymphocyte populations after sepsis." (PMID 30730978, 2019). "Absolute numbers of CD4+ T cells were lower in patients with infection and sepsis compared to controls (p<0.001)." (PMID 31658288, 2019). "CD4+ T cells expressing IL-23 receptor were lower in patients with sepsis compared to patients with infection alone (p = 0.007)." (PMID 31658288, 2019).
Sepsis (continued). "We identified a differential impact of the systemic and mucosal DCs on proliferating allogenic CD4 T cells in a mouse model of sepsis." (PMID 31323786, 2019). "In contrast, 4-PBA decreased the expression of GRP78 and cleaved caspase-3 and amplified the protective effect of Mdivi-1 treatment on CD4+ T cells during sepsis." (PMID 31263382, 2019). "Compared with the control group, the sepsis group exhibited obviously higher PD-1 expression levels on both CD4+ and CD8+ T cells (P < 0.05)." (PMID 31440257, 2019). "In conclusion, our study demonstrated that mucosal DCs were superior to systemic DCs in proliferating allogeneic CD4 T cells in sepsis." (PMID 31323786, 2019). "In CD4+ T cells, IL-23R expression was greater in patients with infection than sepsis (p = 0.005), while in CD8+ T cells, IL-23R expression was greater in patients with sepsis than with patients with infection (p = 0.04) and controls (p<0.001)." (PMID 31658288, 2019). "Based on these results, it can be also be deduced that the functionality differed between systemic and mucosal DCs, and was manifested as the change in CD4 T-cell responses during this particular 24-hour period of sepsis." (PMID 31323786, 2019). "CD4+ T cell exhaustion has been typified by T cells that have severely impaired effector functions and has been found in patients with sepsis." (PMID 31611560, 2019). "CM CD4+ T cell counts were lower in patients with sepsis than in healthy controls (p<0.001) and lower in patients with infection than healthy controls (p<0.001)." (PMID 31658288, 2019). "Not only the number of CD4+ T cell populations but also the function of the remaining lymphocytes is reduced during sepsis." (PMID 31611560, 2019). "Sepsis leads to uncontrolled apoptosis-induced depletion of CD4+ T cells, and some remaining cells are rendered dysfunctional or exhausted due to the prolonged exposure to excessive pro- and anti-inflammatory cytokines." (PMID 31611560, 2019). "Studies have found that CD4+ T cells in sepsis model mice had insufficient autophagy, though autophagosomes were increased." (PMID 31507440, 2019). "The immune cells displaying marked depletion during sepsis include B cells, CD4+, and CD8+ T cells and dendritic cells in lymphoid organs such as the thymus, spleen and lymph nodes." (PMID 31281814, 2019). "Because regulatory T cells are thought to involve in immuno-paralysis in the late phase of sepsis, we have attempted to measure expression of FoxP3 in the CD4 T cells proliferated or skewed by IL-1β." (PMID 31323786, 2019). "Our data suggest CLP-induced sepsis impacts humoral immunity by affecting the number and function of both Ag-specific B cells and CD4 Tfh cells." (PMID 30429857, 2018). "We next determined how sepsis affected the ability of the PE-specific B cells and 2W1S:I-Ab-specific CD4 T cells to respond after immunization with a CFA emulsion containing the MHC II-restricted 2W1S56−68 peptide coupled to PE." (PMID 30429857, 2018). "To assess the function of the antigen-receptor following SIRT1 treatment during sepsis immune tolerance, we measured IFNγ production from total T cell antigen-receptor-stimulated T cells (including CD4+ and CD8+)." (PMID 30069485, 2018). "Our findings also demonstrate that CD43 drives a TH1 phenotype, as CD43-/- demonstrate significantly decreased IL-2+ CXCR3+ CD4+ (TH1-like) cells with a concomitant increase in IL-4+ CCR4+ CD4+ (TH2-like) cells in sepsis." (PMID 30226896, 2018). "CD4 T cells and B cells are among the array of immune cells that experience reductions in number and function during sepsis." (PMID 30429857, 2018). "The immune dysfunction of CD4+ T cells is the primary cellular mechanism behind sepsis and sepsis-induced multiple organs dysfunction syndrome (MODS)." (PMID 29859104, 2018).
Sepsis (continued). "Studies in mice and humans indicate that adaptive immunity T cells also become tolerant during sepsis, variously called “anergy” in CD4+ Th1 effector cells and “exhaustion” in CD8+ cytotoxic T cells." (PMID 30069485, 2018). "Our current results also showed a significant loss of CD4 T cells at day 1 after CLP and sustained this loss at day 3 after sepsis." (PMID 30052667, 2018). "In the current study, we aim to investigate the role of ghrelin for promoting the proliferation of CD4 T cells after sepsis." (PMID 30052667, 2018). "Proportion of B and CD4+ T cells that express PD-1, PD-L1 and PD-L2 in patients with sepsis compared to healthy controls." (PMID 29661225, 2018). "In sum, SPADE analysis demonstrates that relative to non-cancer controls, cancer mice contained more resting memory CD4+ T cells, more activated CD4+ effectors, and fewer naïve CD4+ T cells during sepsis." (PMID 29338031, 2018). "2W1S:I-Ab-specific CD4 T cells have reduced proliferative capacity and cytokine production after sepsis, as well has developing changes within the TCR Vβ repertoire." (PMID 30429857, 2018). "Our finding on ghrelin-mediated induction of proliferation of CD4 T cells isolated from the septic mice spleen also confirmed the immunostimulatory role of ghrelin in sepsis." (PMID 30052667, 2018). "We also report results that are consistent with the published literature such as higher PD-1 and PD-L1 expression in CD4+ T cells in sepsis compared with controls, which gives external validity to our report." (PMID 29661225, 2018). "Our data suggest CLP-induced sepsis impacts humoral immunity by affecting the number and function of both antigen-specific B cells and CD4 Tfh cells, further defining the period of chronic immunoparalysis after sepsis induction." (PMID 30429857, 2018). "In the present study, we show that the immunosuppressive effects of constitutive vagus nerve activation in sepsis surviving mice are mediated through an increased number of CD4+ ChAT+ T cells." (PMID 30237803, 2018). "Immunophenotyping of CD4 and CD8 T cells and monocytes was performed to quantitate expression of immunologic markers associated with immunosuppression in patients with sepsis." (PMID 29944697, 2018). "Our data revealed that cyclin B1was not altered at day 1 after CLP but significantly reduced at day 3 after sepsis, which is correlated with lower proliferation of CD4 T cells at day 3 after CLP." (PMID 30052667, 2018). "Human ghrelin plays an important role in reestablishing the proliferation of CD4 T cells and serves as a promising therapeutic agent in sepsis." (PMID 30052667, 2018). "Second, the ability of three immuno-adjuvants with distinct mechanisms of action to reverse CD4 and CD8 T cell dysfunction, a pathophysiological hallmark of sepsis, was evaluated." (PMID 29944697, 2018). "Here, we demonstrated the beneficial role of ghrelin in young septic animals in terms of reversing the deficit of CD4 T cells in spleen during sepsis through the restoration of their maladaptive proliferative ability." (PMID 30052667, 2018). "Data examining the B cell and CD4 T cell compartments at the “total population” level suggest the immune system has returned to its pre-sepsis state by day 30 in terms of B cell and CD4 T cell numbers." (PMID 30429857, 2018). "Higher expression of PD-1 by memory subpopulations of B cells and CD4+ T cells, with normal soluble PD-1 and PD-L1 in patients with sepsis, are novel findings." (PMID 29661225, 2018). "The extent of Tfh cell differentiation by the 2W1S:I-Ab-specific CD4 T cells after 2W1S-PE/CFA immunization was also impaired by sepsis." (PMID 30429857, 2018). "With this clinical information in mind, we wanted to further investigate how sepsis affects the generation of a primary CD4 T cell-dependent B cell response using the CLP mouse model of polymicrobial sepsis." (PMID 30429857, 2018).
Sepsis (continued). "Taken together, these data suggest that sepsis differentially affects CD4+ versus CD8+ T cells during the early immunosuppression." (PMID 30069485, 2018). "Indirect evidence of defective CD4 T cell function has come from other studies describing altered humoral responses after sepsis, specifically in terms of Ag-specific immunity (e.g., T cell-dependent Ab responses)." (PMID 30429857, 2018). "“Help” from follicular helper (Tfh) CD4 T cells to B cells is needed for productive and protective humoral immunity, but there is a paucity of data defining the effect of sepsis on a primary CD4 T cell-dependent B cell response." (PMID 30429857, 2018). "While the impact of sepsis on several lymphoid populations has been explored, including work from our labs examining the effect of sepsis on CD4 and CD8 T cell responses, the influence of sepsis on the NK-cell compartment remains understudied." (PMID 30379932, 2018). "A key finding of our present study in critically ill adult patients with sepsis was higher expression of PD-1/PD-L in the lymphocyte subsets associated with memory status, i.e. CD27+ B cells and CD27- CD4+ T cells." (PMID 29661225, 2018). "We therefore measured PD-1, PD-L1 and PD-L2 surface expression on CD27+ and CD27- subsets of CD4+ T and B lymphocytes using flow cytometry in adult patients with sepsis on the intensive care unit (ICU)." (PMID 29661225, 2018). "Our group previously demonstrated the CD4 T cells profiles in septic mice from 5 h to 3 days after CLP and found that the decrease of CD4 T cells in sepsis was accompanied by a gradual reduction of CD4 T cell proliferation rates." (PMID 30052667, 2018). "In contrast to the sepsis-induced changes in CD4+ T cells at 30 h, the frequency and absolute cell numbers of CD8+ T cells were similar between sham and CLP (p = 0.79 and p = 0.99, resp)." (PMID 30069485, 2018). "The decrease of CD4 T cell proliferation in sepsis was restored by injection of ghrelin into septic animals, suggesting ghrelin plays an important role to maintain CD4 T cell numbers." (PMID 30052667, 2018). "One of the major mechanisms of decreasing the frequencies of CD4 T cells during sepsis is through their apoptosis." (PMID 30052667, 2018). "On the other hand, CD4 T cell proliferation was slightly decreased at day 1 after sepsis, while it was remarkably reduced on day 3 after CLP as compared to day 1 CLP samples." (PMID 30052667, 2018). "Many mechanisms are responsible for sepsis‐induced immunosuppression, including apoptosis of immune cells, increased regulatory T cells and expression of programmed cell death 1 on CD4+ T cells, and cellular exhaustion." (PMID 30238076, 2018). "Clinical data show acute reduction in both CD4 T cells and B cells in sepsis patients, as well as IgM levels in the circulation." (PMID 30429857, 2018). "Sepsis-induced apoptosis of DCs, CD4+ and CD8+ T cells and B cells occurs in primary immune organs such as blood, bone marrow, spleen, and thymus, resulting in an overwhelming depletion of immune cells." (PMID 30555806, 2018). "Several groups have reported an over-expression of PD-1 on T cells, including CD4+ and Tregs, and PD-L1 on monocytes in adults with sepsis and septic shock compared to healthy adults." (PMID 30555806, 2018). "This strongly suggests that the level of proliferation of CD4 T cell plays an important role in sepsis outcome." (PMID 30052667, 2018). "Future studies on the detection of these cell cycle regulatory proteins in purified CD4 T cells will provide more deep insights into the role of ghrelin on murine CD4 T cell proliferation in sepsis." (PMID 30052667, 2018). "HSYA treatment appears to improve sepsis-induced immunosuppression through inhibiting CD4+ T lymphocyte apoptosis." (PMID 28932195, 2017). "In conclusion, HSYA was an effective therapeutic agent in ameliorating sepsis-induced apoptosis of CD4+ T lymphocytes probably through its anti-inflammatory and anti-apoptotic effects." (PMID 28932195, 2017).
Sepsis (continued). "Compared to individuals who survive an episode of sepsis, in humans who die from sepsis there is more lymphocyte (specifically CD4+ cells) apoptosis." (PMID 29163354, 2017). "The sepsis-induced accumulation of CD4+ DCs in the bone marrow was completely blocked upon application of FTY720." (PMID 29218051, 2017). "This study reveals an alternative mechanism in CD4+ T cell apoptosis in sepsis and provides insight for the development of novel interventional strategies to prevent apoptosis of CD4+ T cells in sepsis." (PMID 29358849, 2017). "Although the median CD4 count among women who died of puerperal sepsis in our study was higher than the median CD4 count overall, less than half were on ART at the time of death." (PMID 29178578, 2017). "In the current study, we stated that Mfn2 acted as a negative regulatory factor of autophagy and prompted apoptosis of CD4+ T cells in sepsis." (PMID 29358849, 2017). "The frequency and the absolute number of splenic CD4+Foxp3+ Treg cells were marked reduced in Il10−/− sepsis-surviving mice at day 15 after CLP." (PMID 28374774, 2017). "Sepsis resulted in a decrease in the absolute count of splenic CD4+ T cells at 24 hours post sepsis compared to sham mice (p = 0.0012)." (PMID 29232699, 2017). "Splenocytes harvested from deceased sepsis patients demonstrate reduced numbers of CD4+ and CD8+ lymphocytes, due to substantial apoptosis." (PMID 29163354, 2017). "A number of CD4+ T lymphocytes are exhausted by the numerous inflammatory mediators which are released during sepsis." (PMID 28932195, 2017). "First, an autophagy process in CD4+ T cells is insufficient during sepsis despite an increase of autophagosomes." (PMID 27618275, 2017). "Among the HIV‐infected women who died of pregnancy‐related sepsis, the median antepartum CD4 count was 236 cells/μl (IQR 110 to 325), and 10/25 (40.0%) were on ART." (PMID 29178578, 2017). "Our results indicate that HSYA treatment improves sepsis-induced immunosuppression via inhibiting CD4+ T lymphocytes apoptosis under septic conditions." (PMID 28932195, 2017). "We further examined the impact of FTY720 on the distribution of CD4+ T cells in the bone marrow during sepsis." (PMID 29218051, 2017). "At day 15 after CLP, a significantly higher frequency and an absolute number of CD4+Foxp3+ Treg cells expressing ST2 were found in the spleen of sepsis-surviving mice as compared to naive mice." (PMID 28374774, 2017). "Apoptosis of CD4+ T cells is a primary pathophysiological mechanism of immune dysfunction in the pathogenesis of sepsis." (PMID 29358849, 2017). "To investigate the role of autophagy in sepsis, we generated T cell–specific autophagy knockout mice (CD4-Cre/Atg5f/f) and performed the CLP procedure." (PMID 27618275, 2017). "To confirm the relationship between Mfn2 expression, autophagy level, and apoptosis in CD4+ T cells in sepsis, we cultured CD4+ T cells in vitro with LPS (10, 100, or 1000 ng/ml) or PBS for 24 hours." (PMID 29358849, 2017). "In this regard, CD4 T cells from animals with sepsis that were treated with IL-7 had an increase in CD28 expression and improvement in T cell function." (PMID 26786705, 2016). "Splenocytes from T reg-depleted sepsis mice (given 100 μg anti-CD25 mAb) contained higher percentages of CD4+CD69+, CD8+CD69+ activated T cells and CD3−NK1.1+ CD69+ activated NK cells compared with isotype matched controls." (PMID 26918357, 2016). "Similar to being a risk factor of PrevTB, sepsis also remained an independent risk factor for LITB, even after controlling for the CD4 counts and viral load and children who developed sepsis on ART should be closely screened for TB." (PMID 27232185, 2016). "Because dysregulated CD4 T cell subsets play an important role in the induction and continuance of sepsis, the alteration of CD4 T cell response was also assessed in this study." (PMID 26999192, 2016).